BRCA2 (BRCA2 DNA repair associated)
Diseases named in the same sentence as BRCA2 in open-access papers (continued):
Sharing a sentence is not in itself a finding about the gene and the disease.
serous ovarian cancer (84 papers, 2008 to 2026). "A retrospective cohort study of 474 BRCA1/2 carriers with high-grade serous ovarian cancer also revealed a significantly higher average age at diagnosis for BRCA2 versus BRCA1 mutation carriers (58.4 years vs. 53.3 years, P = .001)." (PMID 40303993, 2025). "The literature does show that OC in women with a BRCA1 or BRCA2 GPV is generally associated with high-grade serous ovarian carcinoma." (PMID 40428378, 2025). "BRCA2-associated high-grade serous ovarian carcinomas (HGSOCs) demonstrated significantly higher rates of pathologic complete response (pCR) as compared to BRCA1-related cancers [8/15 (53%) vs. 7/48 (15%), P = 0.004]." (PMID 40547808, 2025). "Based on these results we tested H2AX expression by immunohistochemistry using paired biopsies that we obtained from a high-grade serous ovarian carcinoma patient carrying a pathogenic somatic mutation in BRCA2 (c.3376 G > T/ p.Glu1126Ter)." (PMID 38789420, 2024). "PEO1 is a well-known OC cell line derived from a BRCA2 mutated high-grade serous ovarian carcinoma (HGSOC) patient." (PMID 37349576, 2023). "Here we report a case of somatic BRCA2 mutation in a patient with high grade serous ovarian carcinoma." (PMID 31577852, 2020). "The finding in our manuscript that 21.3% of serous ovarian cancer patients were germline BRCA1 or BRCA2 mutation carriers is consistent with previous research reporting a 20% and 23% germline mutation rate in HGSC patients." (PMID 29506471, 2018). "It has been estimated that nearly half of high-grade serous ovarian cancers have germ line or somatic mutations in BRCA1 or BRCA2." (PMID 29254281, 2017). "TCGA (The Cancer Genome Atlas) analyses showed that the BRCA1 and BRCA2 mutations in 22% of the high-grade serous ovarian cancer samples triggered a wide range of aberrations in DNA damage repair pathways, such as homologous repair pathway." (PMID 28187748, 2017). "TCGA analysis showed that the BRCA1 and BRCA2 mutations in 22 % of the high grade serous ovarian cancer (HGS-OvCa) samples triggered a wide range of aberrations in DNA damage repair pathways, such as poly (ADP-ribose) polymerase inhibitors (PARPi)." (PMID 26490766, 2015). "Tumor Nmut was associated with treatment response and with both PFS and OS in patients with high-grade serous ovarian cancer carrying BRCA1 or BRCA2 mutations." (PMID 24265793, 2013). "Therefore, this study aimed to investigate the prevalence of germline mutations in BRCA1 and BRCA2 genes among women with high-grade serous ovarian cancer (HGSOC) treated in the Public Health System in Recife, Pernambuco." (PMID 38641594, 2024). "The total number of synonymous and non-synonymous exome mutations (Nmut), and the presence of germline or somatic mutation in BRCA1 or BRCA2 (mBRCA) were extracted from whole-exome sequences of high-grade serous ovarian cancers from The Cancer Genome Atlas (TCGA)." (PMID 24265793, 2013). "High grade serous ovarian cancers are associated with BRCA1 or BRCA2 mutations." (PMID 18208621, 2008). "In contrast, the BRCA1/BRCA2 GDH patient is a 44-year-old female with high-grade serous ovarian cancer at clinical stage FIGO IIIC, tolerated chemotherapy well." (PMID 40777133, 2025). "Several studies in serous ovarian cancer highlight the prognostic and predictive roles of BRCA1 and BRCA2 germlines and somatic mutations in survival and responses to platinum-based treatments." (PMID 39199616, 2024). "As an example, in BRCA2 mutant high-grade serous ovarian cancer PDX cells, the combinations of PARPi with ATRi or CHKi were synergistic and caused tumor growth suppression and in some cases complete remission." (PMID 38906870, 2024).
serous ovarian cancer (continued). "Using the cBioPortal and the same TCGA dataset, we note that BRCA1 (4%) and BRCA2 (5%) are altered in serous ovarian cancer, and the alterations include amplifications and homodeletions." (PMID 36305848, 2023). "The assay was established using high-grade serous ovarian cancer samples for which BRCA1 and BRCA2 mutation status as well as Myriad MyChoice homologous repair deficiency (HRD) status was known." (PMID 37444554, 2023). "In patients with high-grade serous ovarian cancer, a BRCA1 or BRCA2 mutation was found in 22% of tumors." (PMID 37760950, 2023). "Together, these data suggest that only BDP1 of the TFIIIB complex has expression correlating with stages II, III and IV in serous ovarian cancer which interestingly, is similar to BRCA1 and BRCA2, established drivers of serous ovarian cancer." (PMID 36305848, 2023). "In high-grade serous ovarian carcinoma (HGSOC), PARP inhibitors are particularly sensitive to HGSOC with mutations in BRCA1 or BRCA2 (BRCA1/2)." (PMID 37324006, 2023). "Reflex (automatic) BRCA1 and BRCA2 (BRCA1/2) genetic testing of tumour tissue is being completed for all newly diagnosed high-grade serous ovarian cancer (HGSOC) in the province of Ontario, Canada." (PMID 35418215, 2022). "In a cohort of 53 patients with serous ovarian cancer (29 BRCA1-mutated, 8 BRCA2-mutated, 16 HR-proficient), BRCA-mutated tumors exhibited increased CD3+ and CD8+ T cells as compared to HR-proficient tumors." (PMID 34067105, 2021). "Specifically, results of previous studies suggest that patients with high grade serous ovarian cancer and either BRCA1 or BRCA2 mutations have different clinicopathological features, response to treatment, and prognosis." (PMID 34898566, 2021). "It has been estimated that approximately half of high-grade serous ovarian adenocarcinoma samples are defective in HR repair pathway, and these HR defects are largely driven by mutations or epigenetic silencing of BRCA1 and BRCA2 genes." (PMID 29254281, 2017). "The analysis of 47 high grade serous ovarian cancers identified 13 (28%) pathogenic mutations, 8 BRCA1 and 5 BRCA2." (PMID 26745875, 2016). "PEO1, a chemosensitive BRCA2-mutant serous ovarian adenocarcinoma, and PEO4, a reverted BRCA2-proficient line from the same patient after the development of chemotherapeutic resistance, were primarily used for the study." (PMID 27465688, 2016). "According to several studies, the high level of genomic structural alterations is characteristic of BRCA1 or BRCA2 inactivation (so called BRCAness) in triple-negative breast and serous ovarian carcinomas." (PMID 26426992, 2015). "Here, we discuss a therapeutic concept that seeks to disrupt HR capacity via targeting of BRCA1 and BRCA2 functionality in order to reverse platinum resistance in BRCA-proficient high-grade serous ovarian cancers (HGSOC)." (PMID 24624361, 2014). "The vast majority of inactivating mutations that occur in the BRCA/FA pathway in high-grade serous ovarian carcinomas are found in the BRCA1 and BRCA2 genes." (PMID 23587053, 2013). "Moreover, shRNA-mediated depletion of MDC1 resulted in olaparib resistance in the human high-grade serous ovarian cancer cell line PEO1, that carries the BRCA2 c.5193C>G mutation leading to a complete loss of protein stability." (PMID 41408464, 2026).
serous ovarian cancer (continued). "In a study by George and colleagues using gene expression and copy number analysis in a cohort with high-grade serous ovarian cancer, tumors with BRCA1 alterations harbored significantly increased intra-epithelial T-cell infiltration compared to BRCA2-mutated samples." (PMID 40426860, 2025). "Additionally, gene variations containing the BRCA1 gene and BRCA2 gene augment the possibility of a high-degree serous ovarian carcinoma circumstance." (PMID 39199599, 2024). "BRCA1 and BRCA2 play crucial roles in DNA double-strand break repair by homologous recombination, and prevalence of BRCA1/2 mutation in patients with newly diagnosed high-grade serous ovarian cancer is 20-25% (2011,)." (PMID 35466318, 2022). "In high-grade serous ovarian cancer (the most common subtype), 18–30% of all BRCA mutations are reported to be somatic, and when broken down into individual genes, rates of 28 and 26% have been reported for BRCA1 and BRCA2, respectively." (PMID 34979999, 2022). "In the gene list, BRCA1/BRCA2 were reported and may promote neoepitope formation in high-grade serous ovarian cancer." (PMID 35205408, 2022). "For example, susceptibility to high-grade serous ovarian cancer (HGSOC) is driven by mutations in genes that are involved in DNA double strand break repair (BRCA1, BRCA2, BRIP1, RAD51D and RAD51C), and as a consequence these tumors are highly genomically unstable." (PMID 28881617, 2017). "In fact, long survival in high-grade serous ovarian cancer, when it is observed, may be attributable to mutation in either BRCA1 or BRCA2 when these genotypes are coupled with a high tumor Nmut." (PMID 24265793, 2013). "The term “pelvic serous cancer” is used because the majority of BRCA1- and BRCA2-related gynaecologic cancers appear to originate in the fimbrial end of the fallopian tube rather than the ovary, although they have typically been labelled as “serous ovarian cancer” at diagnosis." (PMID 28285341, 2017). "Women with germ-line BRCA1 or BRCA2 mutation are at increased risk of developing ovarian serous carcinoma while a subset of non-familial ovarian serous carcinomas also demonstrate loss of BRCA1 through either somatic mutations or promoter methylation with transcriptional silencing." (PMID 19798417, 2009). "Women (n = 45) with high-grade serous ovarian cancer underwent genetic counseling and DNA sequencing for BRCA1 and BRCA2 genes." (PMID 38641594, 2024). "Contrasting BRCA2, epimutations in the BRCA1 gene are frequently detected in tissue from triple-negative breast (TNBC) and high-grade serous ovarian cancers (HGSOC)." (PMID 40225940, 2024).
serous ovarian cancer (continued). "According to the results of the II generation, we compared the gene sequencing of 3326 bases of BRCA1 gene and the 1342 bases of BRCA2 gene in all females of the III generation in the family and 2 patients with sporadic serous ovarian cancer (control)." (PMID 32356124, 2020). "We used a commercial kit exploring all exons and 50bp exon-intron junctions of BRCA1 and BRCA2 genes, and semiconductor next-generation sequencing (NGS) on DNA from 47 FFPE samples of high-grade serous ovarian cancers." (PMID 26745875, 2016). "Interestingly, BDP1 expression decreased as serous ovarian cancer stage similar to BRCA1 (F = 3.81; Pr(>F) = 2.3 × 10−2) and BRCA2 (F = 12.8; Pr(>F) = 3.95 × 10−6)." (PMID 36305848, 2023). "Analysis of the GEPIA platform demonstrates that both BRCA1 and BRCA2 mRNA are overexpressed in serous ovarian cancer, but this overexpression is not statistically significant." (PMID 36305848, 2023). "In the high-grade ovarian serous carcinoma subgroup, 31.4% of cases harbored a clinically significant mutation (n = 61 cases, 47 BRCA1 and n = 14 BRCA2), whereas only one likely pathogenic BRCA2 alteration was detected in non-high-grade serous carcinoma." (PMID 31653094, 2019). "Women with a strong family history of “serous ovarian cancer”, but no identified BRCA1 or BRCA2 mutation in the family, also have elevated risks of PSC." (PMID 28285341, 2017). "The regulatory effects of BRCA on GR were assessed in 146 serous ovarian cancer patients (28 pairs of BRCA1-mutated or not, 23 pairs of BRCA2-mutated or not, and 22 pairs with hypermethylated BRCA1 promoter or not)." (PMID 24629067, 2014). "The effect of BRCA1 on EGFR was assessed in 146 serous ovarian cancer patients (28 pairs of BRCA1-mutated or not, 23 pairs of BRCA2-mutated or not, and 22 pairs with hypermethylated BRCA1 promoter or not)." (PMID 24321281, 2013). "High grade serous ovarian cancers that have functional BRCA1 or BRCA2 are currently not separable from high grade serous cancers that have loss of function of these proteins, based on routine histopathological examination." (PMID 18208621, 2008). "This study aimed to investigate the efficacy of HRD testing in high-grade serous ovarian carcinoma, tubal, and peritoneal cancer patients who are negative for somatic BRCA1 and BRCA2 mutations and to evaluate the impact of HRD status on Bevacizumab and PARPi therapy response." (PMID 37296748, 2023). "High-grade serous ovarian cancer in carriers of BRCA1 or BRCA2 has a better prognosis than the same disease in non-carriers, and may be more sensitive to cisplatin-based chemotherapy or to PARP inhibitors that target DNA repair." (PMID 24265793, 2013). "In addition, this panel is targeting “hotspot” region of genes that are frequently mutated in human cancer thus other infrequently altered genes but of significance to serous ovarian cancers might have been excluded such as ARID1A, BRCA1, BRCA2, CSMD3, NF1, CDK12, FAT3 and GABRA6." (PMID 25404506, 2014).
ovarian tumors (77 papers, 1999 to 2026). "Pathogenic/likely pathogenic germline variants in the BRCA1 and BRCA2 genes are associated with an increased risk of developing cancer, particularly breast and/or ovarian tumors." (PMID 39980563, 2025). "Routine molecular profiling for deleterious germline variants in BRCA1 and BRCA2 has become an integral component of the diagnostic and therapeutic approach to hereditary breast and ovarian neoplasms." (PMID 39796670, 2024). "Another example is the pathogenic variant p.Lys3326Ter in BRCA2, correlated with a reduced possibility of breast and ovarian tumor when compared to other pathogenic BRCA2 variants." (PMID 38397209, 2024). "Fifteen percent of ovarian tumors carry mutations in BRCA1 or BRCA2, rendering them vulnerable to treatment with PARP inhibitors such as olaparib." (PMID 37568736, 2023). "Histology associations with BRCA1 and BRCA2 variant pathogenicity were further refined by performing the LR analyses in combination with other ovarian tumour characteristics." (PMID 37076566, 2023). "We provide detailed estimates for predicting BRCA1 and BRCA2 variant pathogenicity based on ovarian tumour characteristics." (PMID 37076566, 2023). "PARP inhibitors such as olaparib and pamiparib have been demonstrated to be indicative of monotherapy in patients with ovarian tumor harboring BRCA1 or BRCA2 mutations." (PMID 35910366, 2022). "Although a few studies have been reported to date, this approach has led to the identification of a pan-cancer gene set, a classifier for chronic lymphocytic leukaemia and synthetic lethal genes in BRCA2-associated ovarian tumours." (PMID 34287743, 2021). "PARP inhibitors yield interesting outcomes for patients with ovarian tumors harboring BRCA1 or BRCA2 mutation, but also with other tumors with homologous repair (HR) deficiency." (PMID 34206535, 2021). "BRCA1 and BRCA2 genes are the most common genes defined in literature with certain mutations and lead to an increased risk of breast and ovarian neoplasms." (PMID 34653224, 2021). "One study by Bueno and Mar has explored gene expression variability to identify synthetic lethal genes associated with BRCA2 loss-of-function ovarian tumours." (PMID 34287743, 2021). "As expected, breast and ovarian tumors from BRCA1/2 germline mutation carriers have even higher HR deficiency scores (average value > 50 for BRCA2 and > 60 for BRCA1 mutation carriers)." (PMID 32164626, 2020). "By comparison, 110 genes were differentially expressed genes between BRCA1- and BRCA2-associated ovarian tumours." (PMID 33081408, 2020). "(2017) showed that though most breast or ovarian tumors with germline BRCA1/BRCA2 loss of function mutations respond to DNA damaging agents, some tumors do not show such a response." (PMID 29797793, 2018). "When TCGA tumors were stratified by mutation and tumor type, both BRCA1 and BRCA2 germline mutation-associated breast and ovarian tumors had a significantly higher proportion of BRCA signature (Signature 3) compared to nonBRCA breast and ovarian tumors." (PMID 28831036, 2017). "Herein we report analyses of 160 BRCA1 and BRCA2 germline mutation-associated breast and ovarian tumors." (PMID 28831036, 2017). "Studies of ovarian tumours in women with BRCA1 or BRCA2 mutations have shown that BRCA1 and BRCA2 carriers predominantly develop serous disease." (PMID 27463617, 2016). "Breast and ovarian neoplasms from BRCA1 or BRCA2 mutation carriers are characterized by deficient homologous recombination (HR) of DNA, that makes them particularly sensitive to platinum compounds or inhibitors of poly (ADP-ribose) polymerase (PARP)." (PMID 21819606, 2011). "BRCA1 and BRCA2 mutated ovarian tumors have different gene expression profiles, however, the gene expression profile of sporadic ovarian tumor overlaps with both." (PMID 20843305, 2010).